ANKLE2 (ankyrin repeat and LEM domain containing 2)
Diseases named in the same sentence as ANKLE2 in open-access papers (continued):
Sharing a sentence is not in itself a finding about the gene and the disease.
tumor (5 papers, 2018 to 2025). "Although our study is the first to demonstrate Banf1’s role in tumour cell proliferation, dysregulated expression of several Banf1-interacting, NE-localised proteins, including Man1 and Ankle2, have been correlated with tumour cell proliferation." (PMID 40664994, 2025). "Our data demonstrate that siRNA-mediated depletion of Ankle2, Emerin, and Lemd2 inhibits cell proliferation in a largely tumor-specific manner in TNBC cells." (PMID 38720803, 2024). "Our findings build upon the existing knowledge of the roles of Lem-D proteins in tumor cells and demonstrate the role of several Lem-D proteins: Ankle2, TMPO, Emerin, and Lemd2 in TNBC growth and cell survival." (PMID 38720803, 2024). "Furthermore, our data demonstrates that siRNA-mediated Ankle2 depletion inhibits cell proliferation and induces cell death in a largely tumor-specific manner." (PMID 38720803, 2024). "Based on these observations, it can be hypothesised that compounds which supress Ankle2 levels or activity may provide favourable anti-tumour activity like that of a traditional cell cycle checkpoint inhibitor." (PMID 36205821, 2022). "Although, given Ankle2 is substantially overexpressed in tumour cells, it is possible that specifically targeting Ankle2 may have substantially less off-target toxicity than conventional therapies." (PMID 36205821, 2022).
infection (2 papers, 2025). The state of being infected such as from the introduction of a foreign agent such as serum, vaccine, antigenic substance or organism. "We observe that ANKLE2 localization is drastically shifted to sites of NS4A accumulation during infection and that knockout of ANKLE2 reduces ZIKV replication in multiple human cell lines." (PMID 39804047, 2025). "Strikingly, we found that ANKLE2 distribution became concentrated after infection, with near-perfect overlap with NS4A." (PMID 39804047, 2025). "Our data suggest a model in which ANKLE2 promotes the proper formation of replication organelles during infection, which accelerates viral genome replication and conceals viral dsRNA from immune sensing." (PMID 39804047, 2025). "ANKLE2 co-localizes with ZIKV NS4A during infection, and depletion of ANKLE2 in human cells leads to consistent reduction in ZIKV replication during early genome replication." (PMID 39804047, 2025). "We find ANKLE2 concentrates at sites of NS4A accumulation during infection." (PMID 39804047, 2025). "We speculate that during high MOI infections, the overwhelming amount of virus can overcome the disadvantage posed by ANKLE2 depletion." (PMID 39804047, 2025). "To establish if ANKLE2 has tissue-specific roles in ZIKV replication, we subsequently tested cell lines representative of tissues targeted by ZIKV during human infection." (PMID 39804047, 2025). "We observed modest, but consistent, decreases in ZIKV replication following ANKLE2 knockdown across two ZIKV strains and a range of multiplicities of infection (MOIs)." (PMID 39804047, 2025). "Early protein expression was comparable across all transduced lines in both WT and ΔB1 infections, suggesting that ANKLE2 does not impact the early stage of the vaccinia viral life cycle." (PMID 41251347, 2025).
neurodegenerative disease (1 paper, 2024). A disorder of the central nervous system characterized by gradual and progressive loss of neural tissue and neurologic function. "While the mechanism by which ANKLE2 interacts with and regulates tau is still unclear, these data suggest a potentially important role for ANKLE2 in the development of neurodegenerative diseases." (PMID 38691001, 2024).
ANKLE2 also shares sentences with these, for which no sentence is quoted: congenital Zika syndrome (1 paper); Intrauterine growth restriction (1); neurological disease (1); osteosarcoma (1); prostate adenocarcinoma (1); prostate carcinoma (1); triple-negative breast carcinoma (1).